PNP (purine nucleoside phosphorylase)
Diseases named in the same sentence as PNP in open-access papers (continued):
Sharing a sentence is not in itself a finding about the gene and the disease.
prostate tumors (1 paper, 2014). "PNP (purine nucleoside phosphorylase) was highly expressed in prostate tumors as compared with nonprostate tumor tissues by RT-PCR and potentially functions as an oncogene." (PMID 24949449, 2014).
sickle cell disease (1 paper, 2025). Sickle cell anemias are chronic hemolytic diseases that may induce three types of acute accidents: severe anemia, severe bacterial infections, and ischemic vasoocclusive accidents (VOA) caused by sickle-shaped red blood cells obstructing small blood vessels and capillaries. "Red blood cells (RBCs) contain the highest purine nucleoside phosphorylase (PNP) level per cell volume, yet the role of PNP in the pathogenesis of sickle cell disease (SCD) is incompletely understood, highlighting an important gap in our knowledge of the disease." (PMID 41469749, 2025).
Splenomegaly (1 paper, 2022). Abnormal increased size of the spleen. "Moreover, PNP-KO mice exhibit phenotypes indicative of hyperimmune activation, such as splenomegaly." (PMID 35653193, 2022).
Stroke (1 paper, 2025). Sudden impairment of blood flow to a part of the brain due to occlusion or rupture of an artery to the brain. "Its molecular docking with targets such as XDH and PNP showed stable binding energy, suggesting that it participates in the pathological process of stroke by regulating purine metabolism and oxidative stress." (PMID 40950576, 2025).
toxoplasmosis (1 paper, 2018). A parasitic disease contracted by the ingestion or fetal transmission of toxoplasma gondii. "Molecular docking studies indicated DNA-binding site of hTopoI and hTopoII as possible anticancer targets and purine nucleoside phosphorylase as possible anti-toxoplasmosis target." (PMID 29576720, 2018).
tuberculosis (1 paper, 2025). A chronic, recurrent infection caused by the bacterium Mycobacterium tuberculosis. "In terms of pathogen infection, recent research reported that PNP-1 negatively regulates the expression of genes that are induced by bacterial infection, and PNP from mycobacterium tuberculosis is an attractive target for tuberculosis treatments." (PMID 39860255, 2025).
ulcerative cystitis (1 paper, 2024). "We assessed the efficacy of a purine nucleoside phosphorylase inhibitor, 8-aminoguanine (8-AG), for the treatment of hemorrhagic/ulcerative cystitis." (PMID 38271096, 2024).
viral infection (1 paper, 2025). "PNP knockdown elicited a purine metabolic shift from augmented salvage pathway to de novo synthesis, constraining both viral infection and pro-inflammatory signaling through APRT-AICAR-AMPK activation." (PMID 40517177, 2025).
xanthinuria type I (1 paper, 2025). "Xanthinuria type I (caused by XDH gene defects, OMIM#278300) or type II (MOCOS gene defects, OMIM#603592) as well as purine nucleoside phosphorylase deficiency (PNP gene defects, OMIM#613179) are forms of hypouricemia resulting from impaired synthesis pathways." (PMID 41164817, 2025).
cancer (31 papers, 2008 to 2025). A tumor composed of atypical neoplastic, often pleomorphic cells that invade other tissues. "2'-Deoxyinosine, found after comparison, can inhibit the growth of human cancer cell lines and is related to purine nucleoside phosphorylase (PNP) deficiency." (PMID 39132155, 2024). "High ADA activity might be advantageous to the cancer cells by causing, in association with purine nucleoside phosphorylase (PNP), an increase in hypoxanthine, a substrate for the salvage pathway." (PMID 31547393, 2019). "Purine-nucleoside phosphorylase (PNP) was identified as a cancer marker as plasma PNP levels on average four times higher in cancer patients." (PMID 39641861, 2025). "Additional PNP inhibitors, ulodesine and peldesine, with potency and bioavailability comparable to forodesine, have entered clinical trials for applications beyond cancer treatment, such as arthritis or limiting uric acid accumulation in gout." (PMID 40519286, 2025). "SAMHD1 has, therefore, emerged as a crucial biomarker for the anti-cancer effects of PNP inhibitors." (PMID 40519286, 2025). "It has been noted that PNP inhibitors have lower efficacy against cancer cells in vivo compared to cell culture experimentation." (PMID 40519286, 2025). "Comparison of PNP gene expression between major subclasses of cancer showed that PNP is significantly higher in Her-2 positive and triple negative subtypes than luminal subtypes, suggesting a role of PNP in cancer aggressiveness." (PMID 38167685, 2024). "For example, dysregulation of enzymes involved in this pathway, such as adenosine deaminase (ADA) and purine nucleoside phosphorylase (PNP), has been shown to promote tumor growth and metastasis in certain types of cancer." (PMID 39330508, 2024). "Cancer cells transduced by Ad5‐PNP exhibited high‐level PNP activity, which varied depending on the PDX model tested." (PMID 36253876, 2023). "This approach to an enzyme prodrug system allows for systemic administration of the fusion protein, with accumulation of PNP in the tumor as a result of AV targeting of the tumor vasculature and cancer cells." (PMID 24098491, 2013). "PNP inhibition was hypothesized to selectively elevate deoxyguanosine levels in malignant T cells, leading to dGTP accumulation and cancer cell death." (PMID 40519286, 2025). "PNP is up-regulated in certain cancers, such as pancreatic adenocarcinoma, where it may be a therapeutic target." (PMID 40519286, 2025). "In cancer patients, elevated plasma PNP levels may result from expression by cancer cells, lymphocytes, and macrophages." (PMID 41502507, 2025). "Given that PPAT and PNP are highly expressed in aggressive cancers, their elevated levels in PTB may reflect an increased demand for nucleotides in response to stress." (PMID 40825832, 2025). "Moreover, PNP is active even when a very small fraction of cancer cells (e.g., <2.5% of a tumor mass) express the transgene." (PMID 36253876, 2023). "Its deaminating action may negatively affect the cytostatic activity of anti-cancer drugs such as gemcitabine, but could be annihilated by co-administration of natural nucleosides or a specific PNP inhibitor." (PMID 26322268, 2015). "The assays based on these compounds may be important in view of the recent application of E. coli PNP in cancer gene therapy in the so-called suicidal gene strategy." (PMID 24126376, 2013). "Furthermore, PNP gene is significantly high in different stages of cancer." (PMID 38167685, 2024). "However, the enzyme purine nucleoside phosphorylase may play a role in cancer chemoresistance by catalyzing the degradation of potentially cytotoxic purine analogs." (PMID 38254798, 2024). "The enzymatic component of the fusion, PNP, converts the FDA-approved cancer therapeutic, fludarabine, into a more cytotoxic form." (PMID 24098491, 2013). "Activated PNP would lead to increase rate of cell proliferation, which is not ideal to be used for cancer treatment according to our system." (PMID 22911721, 2012).
cancer (continued). "Here we report on the delivery of two prodrug converting enzymes, purine-deoxynucleoside phosphorylase (PNP) and a fusion protein consisting of yeast cytosine deaminase and uracil phosphoribosyl transferase (FCU1) into cancer cells in culture by L. monocytogenes." (PMID 18402662, 2008). "Additionally, CNV analysis identified amplification of PNP, FCGR3A, and CFHR1 as well as deep deletion of ETV6, CFHR1, and RPS15 as the most frequently detected copy number altered PID-related genes across the four available pediatric cancer cohorts." (PMID 36497424, 2022). "As the PNP-mediated new salvage pathway is also present in mammals, it remains to be tested whether human PNP (counterpart of xapA) is also able to utilize NAM to synthesize NR as an alternative to pathway II (i.e., via pathway IIIb), thus responsible for the slow anti-cancer action of FK866." (PMID 24506841, 2014). "No cytotoxic effect was observed on other cancer celllines (HeLa S3, HL60, HepG2) or primary PBMCs for up to 10 μM.We report the first example of the PNP inhibitor exhibiting over 60-foldselectivity for the pathogenic enzyme (MtPNP) overhPNP." (PMID 37134237, 2023).
tumor (26 papers, 2008 to 2025). "The dNTP-degrading enzyme SAMHD1 protects against cytotoxic dGTP buildup upon deoxyguanosine supplementation: SAMHD1-deficient tumour cells are sensitive to dGTP accumulation caused by deoxyguanosine supplementation and purine nucleoside phosphorylase inhibition." (PMID 35927450, 2022). "Upon the use of a PNP inhibitor, forodesine (foro), a reduction in the bioenergetic activity, proliferation, viability, and tumor-killing activity is obvious in both mouse and human T effector cells cultured in inosine-containing medium." (PMID 41169479, 2025). "When we increased the PNP mRNA dose to 40 μg mRNA/tumor, we observed a dose-dependent increase in PNP activity." (PMID 40221395, 2025). "We synthesized a chemically modified mRNA encoding E. coli PNP, formulated it within LNPIT, and injected intratumorally at a dose of 6 μg/tumor." (PMID 40221395, 2025). "Because PNP activity levels represent a useful correlative endpoint for predicting tumor regressions in vivo, we determined the extent to which Ad5‐PNP mediates expression of functional PNP enzyme." (PMID 36253876, 2023). "Our experiments investigated purine base cytotoxicity, PNP enzyme activity following treatment of malignant tissue, tumor mass regression, viral receptor studies, and transduction by tropism‐modified adenovirus." (PMID 36253876, 2023). "In the present study we biochemically and kinetically characterized M. hyorhinis-encoded CDA and report on a surprising interaction between mycoplasma CDA and purine nucleoside phosphorylase (PNP) activity in mycoplasma-infected tumor cells." (PMID 26322268, 2015). "An alternative enzyme prodrug approach is to target the PNP enzyme to the tumor with a targeting moiety." (PMID 24098491, 2013). "The PNP was strongly expressed in several tumour lesions (Gleason Score 3+4, pT3aN0) and PIN lesions, whereas no or low expression was observed in the normal tissues." (PMID 22068816, 2012). "We reason this could be achieved by transient and tumor-specific expression of purine nucleoside phosphorylase (PNP), an Escherichia coli enzyme that converts fludarabine into 2-fluoroadenine, a potent cytotoxic drug." (PMID 40221395, 2025). "Both experiments suggest PNP as a crucial enzyme in inosine metabolism as a carbon source, which suggests a promising therapeutic strategy to manipulate T-cell metabolism and to enhance anti-tumor immune responses." (PMID 41169479, 2025). "However, NMRGs with significant AUC values (ENPP1, ENPP2, NAMPT, SIRT1, PARP1, NMNAT1, and PNP) were differentially expressed among tumor grades." (PMID 38254798, 2024). "PNP inactivation is synthetically lethal with SAMHD1 deficiency; thus, PNPi may be particularly effective for the treatment of patients stratified by tumor cell SAMHD1 expression." (PMID 35653193, 2022). "Measles virus has also been armed with genes encoding for pro-drug activation such as purine nucleoside phosphorylase (PNP) from E. coli, with GMCSF and IFN β and with IL-12 which acts as an immunomodulator and mediates anti-tumor effects through T-cell activation." (PMID 30697531, 2018). "To address this, we previously developed three enzyme-containing fusion proteins targeted via annexin V to phosphatidylserine exposed on the tumor vasculature and tumor cells, using the enzymes L-methioninase, purine nucleoside phosphorylase, or cytosine deaminase." (PMID 25047949, 2014). "The hexameric purine nucleoside phosphorylase from Bacillus subtilis (BsPNP233) displays great potential to produce nucleoside analogues in industry and can be exploited in the development of new anti-tumor gene therapies." (PMID 22957058, 2012). "Thus, nontoxic adenosine analogues, which are poor substrates for human PNP, can be cleaved to cytotoxic bases specifically in tumor cells transfected with the bacterial hexameric PNP gene." (PMID 22957058, 2012). "Both miRNAs may function as tumour suppressors regulating PNP, an oncogenic gene in PCa." (PMID 22068816, 2012).
tumor (continued). "We found that genetic expression of crucial enzymes in purine metabolism (Hypoxanthine‐guanine phosphoribosyl transferase, HPRT, Xanthine oxidoreductase, XOR, and Purine nucleoside phosphorylase, PNP) were significantly increased in Tumor + WD group." (PMID 39225628, 2024). "Other genes were modulated in a different way in all three SCCs (NMNAT1, NMNAT2, NADSYN1, SIRT3, and CD38) or in two tumor types (NNMT, NMNAT3, ENPP2, PNP, and SIRT1)." (PMID 38254798, 2024). "This cluster functions as a tumor suppressor targeting the same oncogenic genes such as TAGLN2 and PNP." (PMID 24520312, 2014). "For example, the purine nucleoside phosphorylase (PNP), one of convertase enzymes expressed in infected cells could convert prodrugs within the TME into toxic metabolites which eventually diffuse into and destruct adjacent uninfected tumor cells." (PMID 37491263, 2023). "PNP (purine nucleoside phosphorylase), known as a key enzyme in the rescue purine synthesis pathway and catalyzing purine nucleoside phosphorylation between adenine and adenosine reversibly, was up-regulated in both shikonin-treated groups in SW620 cells and tumor tissues." (PMID 33281602, 2020).
infection (11 papers, 2008 to 2025). The state of being infected such as from the introduction of a foreign agent such as serum, vaccine, antigenic substance or organism. "At 2 weeks after infection, metabolites associated with the purine nucleoside phosphorylase pathway were increased." (PMID 36061860, 2022). "Among the siblings carrying the same PNP gene mutation, there were some discrepancies in the severity of infections and immune abnormalities." (PMID 32695102, 2020). "Using the small roundworm C. elegans, we show that infection with natural obligate intracellular pathogens is impaired by loss of pnp-1, the C. elegans ortholog of the vertebrate purine nucleoside phosphorylase (PNP), which is an enzyme involved in salvaging purines." (PMID 33878133, 2021). "Conversely, PNP knockdown by siRNA (siPNP) resulted in an increased level of guanosine, inosine, and adenosine and a reduction of glutamine upon infection." (PMID 40517177, 2025). "Collectively, by metabolite flux analysis, we further demonstrated that, upon infection, PNP inhibition blocked H1N1-enhanced purine salvage while reactivated purine de novo synthesis in alveolar epithelial cells." (PMID 40517177, 2025). "At the 2-week time-point after infection, the purine nucleoside phosphorylase pathway was enriched with a false discovery rate of 0.00587." (PMID 36061860, 2022). "The conversion of MePdR after infection of the mammalian cells with PNP-enzyme secreting Lm reached only 25–55% in all the cell cultures." (PMID 18402662, 2008). "In ovaries, the higher abundance of uric acid after the infection was correlated with the downregulation of two E. sea bass metabolic genes: Purine nucleoside phosphorylase 5a (pnp5a, PNP human ortholog, log2FC: − 1.96) and lactate dehydrogenase b (ldhb, LDHB human ortholog, log2FC: − 1.35)." (PMID 41241706, 2025). "In addition, compared to the control group, a lower level of 15N-labeled ATP was detected in PNP-knockdown cells upon infection." (PMID 40517177, 2025).
metabolic disorders (4 papers, 2009 to 2025). "We found that IAV infection robustly induced nucleotide metabolism rewiring, and PNP inhibition potently reversed the metabolic disorders." (PMID 40517177, 2025).
infectious disease (1 paper, 2023). A disorder directly resulting from the presence and activity of a microbial, viral, or parasitic agent in humans. "Such PNP inhibitorshave a great potential for the treatment of T-cell acute lymphoblasticleukemias (inhibition of hPNP) or infectious diseases (e.g., inhibitionof PNP from various pathogens)." (PMID 37134237, 2023).
neurodegenerative disease (1 paper, 2021). A disorder of the central nervous system characterized by gradual and progressive loss of neural tissue and neurologic function. "Purine nucleoside phosphorylase (PNP) was the unique overexpressed protein in four neurodegenerative diseases (AD, PD, MixD and ALS)." (PMID 34768771, 2021).
PNP also shares sentences with these, for which no sentence is quoted: developmental delay (4 papers); autoimmune hemolytic anemia (3); systemic lupus erythematosus (3); acute lymphoblastic leukemia (2); bacterial infection (2); triple-negative breast carcinoma (2); Alzheimer disease (1); autoimmune lymphoproliferative syndrome (1); B-cell lymphopenia (1); Bloom syndrome (1); cholangiocarcinoma (1); colitis (1); Dystonia (1); endothelial dysfunction (1); Fanconi anemia (1); Fanconi syndrome (1); Friedreich ataxia (1); glioma (1); head and neck tumors (1); hearing loss (1); heart failure (1); hematologic malignancies (1); idiopathic thrombocytopenic purpura (1); liver diseases (1); lymphoma (1); macrophage activation syndrome (1); metastatic prostate carcinoma (1); microsporidia infections (1); molybdenum cofactor deficiency (1); nephritis (1).
A further 13 diseases each share a sentence with PNP in 1 paper.